PPM1A (protein phosphatase, Mg2+/Mn2+ dependent 1A)
Diseases named in the same sentence as PPM1A in open-access papers (continued):
Sharing a sentence is not in itself a finding about the gene and the disease.
prostate carcinoma (4 papers, 2014 to 2019). A carcinoma that arises from epithelial cells of the prostate gland. "In human prostate cancer, distant metastases exhibit significantly lower PPM1A expression levels compared to primary tumors." (PMID 29799477, 2018). "Previous studies have shown that lower expression of PPM1A is involved in human cytotrophoblast cell invasion and migration and that decreased PPM1A expression inhibits prostate cancer metastases." (PMID 25026293, 2014). "These experiments suggest that restoration of PPM1A expression may have clinical utility as an anti-tumor strategy, at least in prostate cancer." (PMID 29799477, 2018).
Stroke (4 papers, 2020 to 2022). Sudden impairment of blood flow to a part of the brain due to occlusion or rupture of an artery to the brain. "The hypomethylation of TNF receptor-associated factor 3 (TRAF3) and of protein phosphatase 1A (PPM1A) is also related to increased stroke occurrence in patients treated with antiplatelet drugs." (PMID 31941075, 2020).
viral myocarditis (3 papers, 2025). Myocarditis that is caused by an infection with a viral agent. "Moreover, deletion of Mid1 decreased susceptibility of mice to viral myocarditis, pneumonia, and herpes simplex encephalitis by enhancing the production of type I IFN through its interaction with protein phosphatase 1A (PPM1A) responsible for dephosphorylation of TANK binding kinase 1 (TBK1)." (PMID 40443734, 2025).
atherosclerosis (2 papers, 2018 to 2023). A disease characterized by the build-up of fatty material and calcium deposition in the arterial wall resulting in partial or complete occlusion of the arterial lumen. "This suggests that identification of drugs that would induce upregulation of PPM1A expression to inhibit monocyte-to-macrophage differentiation could be valuable to treat atherosclerosis." (PMID 29343725, 2018).
liver fibrosis (2 papers, 2019 to 2024). "Since PPM1A deficiency is involved in several diseases, PPM1A activation by small molecules might be a promising strategy for the treatment of cancer and/or liver fibrosis." (PMID 31336763, 2019). "Enhancing PPM1A expression by targeting TRIM52 is a promising strategy to block liver fibrosis." (PMID 39199424, 2024).
metastatic prostate carcinoma (2 papers, 2016 to 2019). A carcinoma that arises from the prostate gland and has spread to other anatomic sites. "Previous study indicated that metastatic prostate cancer had lower PPM1A expression compared with primary tumor." (PMID 30867653, 2019).
Oral Squamous Cell Carcinoma (2 papers, 2021). "Overall our observations indicate that overexpression of PPM1A exerts oncogenic effects, but mimicking miR-487a-3p exerts anti-oncogenic impacts in oral squamous cell carcinoma cells by alleviating the cell growth and cell invasion." (PMID 33724144, 2021). "The miR-487a-3p overexpression inhibits OSCC cell growth and invasion, miR-487a-3p targets the PPM1A gene in OSCC, and the miR-487a-3p overexpression may rescue the oncogenic effects of PPM1A on oral squamous cell carcinoma cells." (PMID 33724144, 2021).
osteosarcoma (2 papers, 2021). A usually aggressive malignant bone-forming mesenchymal neoplasm, predominantly affecting adolescents and young adults. "PPM1A is also regulated by miR-135b in promoting proliferation and invasion of osteosarcoma cells." (PMID 33724144, 2021). "Furthermore, miR‐522 could facilitate osteosarcoma tumorigenesis through regulating PPM1A expression." (PMID 33369228, 2021).
Parkinson disease (2 papers, 2013 to 2024). A progressive degenerative disorder of the central nervous system characterized by loss of dopamine producing neurons in the substantia nigra and the presence of Lewy bodies in the substantia nigra and locus coeruleus.
sacroiliitis (2 papers, 2019 to 2020). "Furthermore, the serum levels of anti-PPM1A antibodies were higher in AS patients with high-grade sacroiliitis than those with low-grade sacroiliitis." (PMID 33297507, 2020). "Furthermore, AS patients with grade 3 or 4 radiographic sacroiliitis, the levels of anti-PPM1A were also higher than in those with grade 2 radiographic sacroiliitis." (PMID 30723468, 2019).
adenovirus infection (1 paper, 2022). "Additionally, we found there was more PPM1A expression in WT BMDM than TRIM18 KO BMDM without and with CVB3 or adenovirus infection." (PMID 35909127, 2022).
Alzheimer disease (1 paper, 2024). A progressive, neurodegenerative disease characterized by loss of function and death of nerve cells in several areas of the brain leading to loss of cognitive function such as memory and language. "Although the relationship between ITSN1 and PPM1A and aging has not yet been explored, diseases related to it, such as Alzheimer’s disease, usually occur along with aging, which may indicate that ITSN1 and PPM1A has a certain correlation with aging." (PMID 38926642, 2024).
carcinomas in situ (1 paper, 2014). "We found that PPM1A expression was significantly lower in muscle-invasive recurrence compared to primary carcinomas in situ." (PMID 25026293, 2014).
cervical cancer (1 paper, 2021). A primary or metastatic malignant neoplasm involving the cervix. "There exists evidence that miR-135b leads to cervical cancer cell transformation and downregulated miR-135b expression could inhibit the proliferation and invasion of tumor cells by upregulating PPM1A." (PMID 34149809, 2021). "The remaining 10 genes (i.e., YJEFN3, SPATA5L1, C5orf55, PPM1A, IMMP1L, ZNF330, PPIP5K2, ESCO2, FICD, and ZNF225) are not directly reported to be related to the survival risk of cervical cancer in previous literature." (PMID 34149809, 2021).
co-infection (1 paper, 2016). "Specifically in the context of HIV-1/Mtb co-infection, our data show that PPM1A plays a critical role at the interface of HIV-1/Mtb co-infection." (PMID 27004401, 2016). "The most interesting individual signal on the kinome array representing a possible link to HIV-1/Mtb co-infection was the up-regulation of Protein Phosphatase, Mg2+/Mn2+-dependent 1A (PPM1A) expression (Z-ratio = 8.6)." (PMID 27004401, 2016). "The significance of our findings rests with the possibility that controlling the regulatory function of PPM1A by drug intervention has the potential to interrupt the notorious amplification cycle of HIV-1/Mtb co-infection." (PMID 27004401, 2016).
colitis (1 paper, 2021). Inflammation of the colon. "In the late stage of colitis, PPM1A KO mice displayed an increased score of daily disease activity index (DAI) of colitis and more severity in body weight loss, suggesting the presence of more severe inflammations and/or defects in intestinal regeneration." (PMID 33630828, 2021). "We thus evaluated functions of the PPM1A-mediated Hippo signaling regulation in DSS-induced colitis by utilizing the PPM1A KO mice." (PMID 33630828, 2021). "It is even surprising that PPM1A is so critical for the regeneration of intestines and livers and disease phenotypes of colitis." (PMID 33630828, 2021). "Because PPM1A also functions as a critical negative regulator of TGF-β/Smad signaling and innate nucleic acid sensing, we used pharmacological methodology to analyze their individual contributions to these severe colitis phenotypes observed in PPM1A KO mice." (PMID 33630828, 2021). "Pharmacological inhibition of Hippo-YAP signaling, but not the inhibition of TGF-β signaling or the IFN-I pathway, entirely survived PPM1A KO mice upon DSS-induced colitis challenge." (PMID 33630828, 2021). "Taken together, these genetic and pharmacological analyses in murine colitis model suggest an indispensable role of PPM1A in ameliorating the progression of colitis, via PPM1A-mediated suppression of Hippo signaling." (PMID 33630828, 2021). "To confirm that PPM1A interacts with Hippo signaling genetically, we attempted to examine the colitis phenotypes of Ppm1a−/−/Lats1+/− mice obtained by crossing the PPM1A KO mice with LATS1 heterozygotes." (PMID 33630828, 2021). "PPM1A deficiency resulted in a markedly reduced level of intestinal epithelium by which it contained the nuclear YAP, and impeded the colon regeneration upon colitis." (PMID 33630828, 2021). "Administration of XMU-MP-1 entirely recovered the severe colitis phenotypes in PPM1A KO mice, including the daily DAI and body weight loss, largely prevented the DSS-induced disruption of crypts and villus architectures in PPM1A KO mice, and nicely maintained the proliferating intestinal epithelium." (PMID 33630828, 2021). "Furthermore, a specific inhibitor of MST kinases, or half-deficiency of LATS1, well rescues the defective phenotype in PPM1A KO mice, demonstrating that the key role of the PPM1A-YAP axis in guts and livers and diseases such as colitis." (PMID 33630828, 2021). "Furthermore, blockade of TGF-β signaling or the IFN-I production failed to rescue these severe symptoms of colitis in mice without PPM1A." (PMID 33630828, 2021). "Notably, the majority of PPM1A KO mice failed to survive and died during the late stage of colitis, in a sharp distinction with wild-type mice that were mostly survived." (PMID 33630828, 2021). "Accordingly, genetic ablation or depletion of PPM1A in cells, organoids, and mice elicited an enhanced YAP/TAZ cytoplasmic retention and resulted in the diminished cell proliferation, severe gut regeneration defects in colitis, and impeded liver regeneration upon injury." (PMID 33630828, 2021).
colorectal tumor (1 paper, 2025). "However, other regulators modulating ACAT1 pS60 may exist, and we are optimistic that PPM1A or other yet-unidentified regulators will hold promise for inhibiting colorectal tumor growth via specific induction of ACAT1 nuclear translocation." (PMID 40289129, 2025).
dopaminergic neuroblastoma (1 paper, 2021). A neuroblastoma associated with increased dopamine excretion. "We next examined whether DYRK1A binds to two PPM family proteins (PPM1A and PPM1B) in other mammalian cells, such as dopaminergic neuroblastoma SH-SY5Y cells." (PMID 33380426, 2021).
endometriosis (1 paper, 2024). The growth of functional endometrial tissue in anatomic sites outside the uterine body. "Notably, TRIM59 in ectopic lesions, through ubiquitination, regulates PPM1A degradation, activating the TGF-β/SMAD2/3 pathway and thus promoting fibrosis in endometriosis." (PMID 38735939, 2024).
gastric cancer (1 paper, 2024). A primary or metastatic malignant neoplasm involving the stomach. "The suppression of PPM1A counteracted the inhibitory effects of TRIM65 knockdown on cancer progression, suggesting that TRIM65 facilitates gastric cancer progression by degrading PPM1A." (PMID 39768197, 2024).
Insulin resistance (1 paper, 2020). Increased resistance towards insulin, that is, diminished effectiveness of insulin in reducing blood glucose levels. "The expression of PPM1A significantly decreases in two models of insulin resistance: diet-induced obese (DIO) mice and db/db mice, in which it negatively correlates with pSer273." (PMID 32024237, 2020).
liver cancer (1 paper, 2016). An epithelial or non-epithelial malignant neoplasm that arises from the liver. "Similarly, our study with human HCC specimens show that PPM1a expression in liver cancer tissue is weakened, further supporting PPM1a as a tumor suppressor." (PMID 27121309, 2016).
Obesity (1 paper, 2020). Accumulation of substantial excess body fat. "Although further studies are required to elucidate the relationship between PPM1A and metabolic diseases, our study proposes that PPM1A may represent a promising therapeutic target for obesity and metabolic disorders." (PMID 32024237, 2020).
osteoarthritis (1 paper, 2023). A noninflammatory degenerative joint disease occurring chiefly in older persons, characterized by degeneration of the articular cartilage, hypertrophy of bone at the margins and changes in the synovial membrane. "TGF-β signaling is crucial for modulating osteoarthritis (OA), and protein phosphatase magnesium–dependent 1A (PPM1A) has been reported as a phosphatase of SMAD2 and regulates TGF-β signaling, while the role of PPM1A in cartilage homeostasis and OA development remains largely unexplored." (PMID 36752205, 2023).
papillary adenocarcinoma (1 paper, 2008). A morphologic variant of adenocarcinoma. "In contrast, those promoting Ca++ desensitization, such as the MLCPs (Ppm1a, Ppm1g, Pp2r2d, Ppp2r1a, Ppp1 catalytic subunit and Cdc42), were more highly expressed in the papillary adenocarcinoma tumors." (PMID 18811984, 2008).
spondyloarthropathy (1 paper, 2024). A group of inflammatory rheumatic diseases associated with arthritis and enthesitis, and often involving the axial skeleton. "We did not identify PPM1A or other autoantigens in our study, potentially due to our mix of spondyloarthropathy subjects, our use of multiple disease controls, or our inclusion of only linear peptides, which do not include conformational epitopes." (PMID 39449329, 2024).
triple-negative breast carcinoma (1 paper, 2019). An invasive breast carcinoma which is negative for expression of estrogen receptor (ER), progesterone receptor (PR), and human epidermal growth factor receptor 2 (HER2). "Inhibition of CDK4/6 and CDK2 function using biochemical inhibitors suppresses the growth of triple negative breast cancer cells with low PPM1A, suggesting PPM1A as a biomarker to predict sensitivity to CDK inhibitors for more effective treatment of triple negative breast cancer." (PMID 31372497, 2019).
cancer (22 papers, 2008 to 2026). A tumor composed of atypical neoplastic, often pleomorphic cells that invade other tissues. "Because many axon guidance molecules are also involved in regulation of cell migration and apoptosis, the enrichment of axon guidance genes among network neighbors may be informative for the association of PPM1A with cancer." (PMID 27333808, 2016). "At the same time, pan-cancer analysis also shows that PPM1A, DAPK1, FBP1, PYHIN1, ALPL and SMCHD1 have significant amplification in PCa." (PMID 30867653, 2019). "We proposed a new mechanism by which HCV protein NS3 enhances cancer cell invasion and migration through promoting the ubiquitination and degradation of PPM1A." (PMID 28283039, 2017). "PPM1A, similar to many other phosphatases, is able to regulate multiple cellular functions, such as differentiation, proliferation, and immunity, that have been intensively investigated in cancer and metabolic diseases." (PMID 36752205, 2023). "In different cancers, PPM1A has been evinced to serve as a tumor suppresser or promoter." (PMID 34154607, 2021). "We also found other cancer-associated signaling pathways enriched, such as “signaling by PTK6” (Reactome pathway, P = 5.26e-05) and “ErbB signaling pathway” (KEGG pathway, P = 1.26e-04) among PPM1A neighbors." (PMID 27333808, 2016). "Animal experiments further proves that PPM1a inhibits metastasis of above cancers." (PMID 27121309, 2016). "The recently identified CDK9-targeted kinases, CDK7, CDK2, and phosphatases, PP1, and PPM1A will likely emerge as novel targets for anti-HIV-1 and cancer therapeutics." (PMID 24524087, 2014). "Rescue of PPM1A expression, conversely, attenuates TGF-β1 signaling and cancer cell invasion." (PMID 29799477, 2018). "The PPM1A protein expression differed between primary superficial tumors and muscle-invasive recurrent cancer tissues with more negative staining among the recurrence samples (p = 0.012)." (PMID 25026293, 2014). "PPM1A, SNRPN, RAB5B, and CAPG were also reported to be related to cancer." (PMID 18237428, 2008). "PPM1A is a repressor of the TGF-β1 pathway is not exclusive to cancer." (PMID 29799477, 2018). "Multiple non-canonical kinases and phosphatases including aPKC, Akt, PP2a, PPM1A and PP1 are known to impact the stability of β-catenin and YAP in intestinal stem cells and multiple cancer cell types." (PMID 38787854, 2024). "How PPM1A is regulated and its specific role in TGF-β1-driven pathophysiologic disorders (e.g., cardiovascular disease, tissue fibrosis, cancer progression/invasion) is not known." (PMID 21829547, 2011).